CRP (C-reactive protein)
Diseases named in the same sentence as CRP in open-access papers (continued):
Sharing a sentence is not in itself a finding about the gene and the disease.
chorioamnionitis (continued). "However, according to recent systemic reviews and a meta-analysis conducted by Lamont's group, maternal serum CRP may not be considered a reliable indicator of either clinical or histologic chorioamnionitis due to the presence of differences among studies." (PMID 25291377, 2014). "When the opposite result was obtained (3 articles), there were some cases of lower F1 gestational age and some cases of lower CRP and WBC, important predictors of chorioamnionitis, in the non-cerclage group." (PMID 38671355, 2024). "Prior systematic reviews have evaluated the role of C-reactive protein (CRP) in PPROM and do not recommend its use for predicting chorioamnionitis." (PMID 32532314, 2020).
lung disease (94 papers, 2007 to 2025). "Men, retreated cases, poor, history of smoking, pulmonary cavity, age ≤ 50 years, BMI ≤ 18.5, CRP ≥ 37.3, farmer, comorbidities, and lung disease history were risk factors for developing MDR-TB." (PMID 40766036, 2025). "Significant associations were observed with various items mainly in lung diseases, such as increased respiratory rate, decreased oxygen saturation, and increased C-reactive protein in both chronic and acute phases." (PMID 38250933, 2024). "LDH and CRP, which are elevated in several pulmonary diseases, have previously been associated with RMPP and the formation of bronchial mucus plugs, and can be used as early predictors of the condition." (PMID 33407216, 2021). "Several studies have reported that serum c-reactive protein (CRP), an inflammatory biomarker, has the ability to predict cardiovascular disease, lung disease, cancer, and all-cause mortality risk in general population." (PMID 31511566, 2019). "The inflammatory mediators implicated in lung disease, including C-reactive protein, fibrinogen, activated complement components, and cytokines (e.g., interleukin 6, interleukin 1, tumor necrosis factor-α) have also been associated with the development of AF." (PMID 23118762, 2012). "In pulmonary diseases (such as TB or bronchiectasis), elevated CRP may reflect the activity of underlying conditions, with active lesions (such as persistent inflammation or uncontrolled infections) increasing the risk of rebleeding." (PMID 41488072, 2025). "Given that extrapulmonary TB is a relatively common manifestation in children, and may be associated with higher blood CRP levels than isolated pulmonary disease, this represents an area for future research." (PMID 39446791, 2024). "Furthermore, a study concluded that CRP seems to be elevated in a minority of myositis subjects—mostly linked to lung diseases and malignancies—whereas another study reported elevated CRP (mean approx. 10 mg/L) in cases with idiopathic inflammatory myopathies." (PMID 37873776, 2023). "Furthermore, our study revealed that CRP might reflect HRQL-associated disease activity in patients with MAC lung disease." (PMID 26635226, 2015). "In conclusion, this study constructed a model for predicting the risk of developing MDR-TB in patients with TB based on sex, age, type of TB treatment, CRP, BMI, smoking history, occupation, lung disease history, pulmonary cavity, comorbidity, and poverty." (PMID 40766036, 2025). "These variables included sex, age, type of TB treatment, BMI, smoking history, occupation, lung disease history, pulmonary cavitation, comorbidity, poverty, and CRP level." (PMID 40766036, 2025). "In contrast, in GA, the CRP level in lung disease was significantly higher than that in laryngopharyngeal and tracheobronchial diseases, with a median value of 2.6 μg/mL (range: 0–21.0 μg/mL)." (PMID 38250933, 2024). "In the present study, the CRP level was significantly elevated in GA compared to GC, and across disease localization, both groups showed significantly increased CRP levels in lung disease." (PMID 38250933, 2024). "Compared to the TD group, the NTD group had a higher prevalence of pulmonary diseases (87.62% vs 73.20%, p=0.009), and significantly higher levels of high-sensitivity C-reactive protein (HCRP) (89.52% vs 59.79%, p<0.001)." (PMID 39600704, 2024). "In GC, the CRP level in lung disease was significantly higher than that in pharyngeal, laryngeal, and tracheobronchial diseases, but the median value was 0.82 μg/mL (range: 0.02–16.56 μg/mL)." (PMID 38250933, 2024). "The C-reactive protein levels were elevated in both groups, primarily in patients with lung disease." (PMID 38250933, 2024). "In those with advanced CF lung disease (n=14), 3 months of ETI treatment reduced plasma IL-6 levels alongside associated reductions in the acute phase proteins C-reactive protein and α1 anti-trypsin, changes that were also apparent at 1 year." (PMID 39687397, 2024).
lung disease (continued). "The correlation between neuron-specific enolase (NSE) and hs-CRP is 0.31, 0.09, 0.07, and 0.11 in the four types of lung diseases, notably that the correlation coefficient in healthy people is higher than in others." (PMID 39333995, 2024). "Dogs with pulmonary coccidioidomycosis in the current study had higher serum CRP concentrations and anticoccidioidal IgG titers compared to dogs with pulmonary disease in the previous study." (PMID 36836327, 2023). "Up to date, it has been shown that in pulmonary diseases marked by inflammatory features, a typical raise in serum CRP level takes place in response to inflammatory cytokines such as interleukin (IL)-6, IL-1 or tumoral necrosis factor (TNF)-α." (PMID 35809152, 2022). "Four hundred and three cases with culture-confirmed pulmonary disease had both strain-type and baseline CRP available, and were included in this analysis." (PMID 27287260, 2016). "Individuals presenting with pre-ATT AFB smear < 2+ and CRP levels < 4.7 mg/L were more than 12 times more likely to exhibit radiographic improvement of lung disease." (PMID 27494953, 2016). "CRP levels, age, %FVC, underlying pulmonary disease, %DLCO, current treatment, and sputum culture significantly predicted physical functioning subscale score, accounting for 56.0 % of the variance." (PMID 26635226, 2015). "Further studies including qualitative assessments are needed to investigate the efficacy of CRP as a marker for progression or treatment response in MAC lung disease." (PMID 26635226, 2015). "HRQL, especially the physical component, was impaired in patients with MAC lung diseases; this appears to be related with current treatment status, positive sputum smear or culture within the previous year, and particularly CRP and age." (PMID 26635226, 2015). "Regarding the physical component summary score, age, CRP levels, %DLCO, sputum culture, and underlying pulmonary diseases were significant predictors, accounting for 47.4 % of the variance." (PMID 26635226, 2015). "Pulmonary diseases with inflammatory features raise the serum CRP level, and there is also evidence of local pulmonary CRP synthesis." (PMID 19503785, 2009). "Recent omics studies have provided a series of biomarkers of systemic inflammation reflecting important physiological roles in lung physiology, among which plasma C-reactive protein (CRP) may participate in the pathogenesis of various pulmonary disorders." (PMID 40136421, 2025). "In GA, among lung diseases, the CRP levels in bronchopneumonia and aspiration pneumonia were significantly greater than those in pulmonary edema (cardiogenic and non-cardiogenic), with median values of 4.0 μg/mL (range: 0.3–14.3 μg/mL) and 2.6 μg/mL (range: 0.3–13.1 μg/mL), respectively." (PMID 38250933, 2024). "The specific reason dogs in our study with pulmonary disease had higher serum CRP concentrations than those with dissemination is unknown and likely multifactorial." (PMID 36836327, 2023). "Similarly, serum CRP concentrations were higher in dogs with pulmonary disease compared to those with dissemination." (PMID 36836327, 2023). "The ROC analysis revealed a good area under the curve for circulatory C1INH to discriminate neonatal lung disease group from healthy neonates, and this discriminative ability was enhanced when combined with the traditional circulatory marker levels of IL-6 and CRP." (PMID 35669402, 2022). "Besides, in the sensitivity analysis, we excluded participants who had lung diseases and CVD to avoid reverse causation, because people with chronic diseases are likely to have high CRP levels in their serum and low PA." (PMID 31906909, 2020). "Individuals presenting with pre-ATT AFB smear < 2+ and CRP levels < 4.7 mg/L were ten times more likely to exhibit radiographic improvement of lung disease compared to those with higher values of these parameters (Relative risk: 10.0, 95 % CI: 2.4–40.0; p = 0.002)." (PMID 27494953, 2016).
lung disease (continued). "Importantly, we detected a synergistic effect of low AFB counts and low CRP values on odds for improvement in lung disease." (PMID 27494953, 2016). "Serum CRP concentrations were higher in dogs with coccidioidomycosis than controls, indicating that all dogs enrolled in this study at the time of diagnosis exhibited systemic inflammation, and in contrast to the other parameters, it was higher in dogs with pulmonary disease." (PMID 36836327, 2023). "Previous pulmonary disease and granulomatous inflammation were significantly associated with the EBUS-TBNA diagnosis on univariate logistic regression analysis, while age, gender, LN size, smoking history, white blood cell count, and C-reactive protein were unrelated to the EBUS-TBNA diagnosis." (PMID 32293480, 2020). "The stepwise multiple regression analysis included age, sex, age-adjusted CCI, BMI, smoking status, disease duration, underlying pulmonary diseases, treatment status (currently treated vs previously/never treated), positive sputum smear or culture, pulmonary function, Hb levels, and CRP levels." (PMID 26635226, 2015). "Collectively, the use of plasma markers of systemic inflammation, especially IL-6 and CRP, provides additional indicators of clinical status and may add to our understanding of the relationship between inflammation and the severity of lung disease in CF patients." (PMID 22333132, 2012). "Data from the Odense Schoolchild Study recently demonstrated that higher levels of CRP at age 20 are associated with greater reduction in FEV1 and FVC over nine years, but the young age of the study population makes it difficult to ascertain risk of future lung disease." (PMID 20625390, 2010). "Alternatively, in non-smokers, high fibrinogen and CRP may mark risk for accelerated age-related decline in lung function, without the development of any specific lung disease." (PMID 20625390, 2010). "We hypothesized that in young adults without lung disease, elevated levels of CRP and fibrinogen in young adulthood would be associated with accelerated decline in lung function over 15 years of follow-up as well as greater risk of COPD in middle age." (PMID 20625390, 2010). "Median CRP levels were 37.8 mg/dL (n = 4; IQR: 28.8–113.3 mg/dL) in patients with a history of pulmonary disease and 5.5 mg/dL (n = 44; IQR: 2.6–24.2 mg/dL) in patients without a history of pulmonary disease (Mann–Whitney U test p = 0.03)." (PMID 39852142, 2025). "Compared to CRP or PCT, microbiota would serve as better biomarkers for assessing therapeutic efficacy and monitoring disease progression in lung diseases, as they are less influenced by prior antibiotic exposure." (PMID 38993672, 2024). "In our work those patients with lung disease presented higher rates of inflammatory serological markers, such as ESR and CRP, in line with previous studies." (PMID 32973236, 2020). "Raised C-reactive protein (CRP) levels and abnormal chest x-ray in patients presenting with influenza-like illness on a background of pulmonary disease should be taken as a sign for possible deterioration and hospital admission." (PMID 32821569, 2020). "Indeed, systemic inflammation might be the link between HDL-cholesterol, LDL-cholesterol and lung function, since the levels of the general inflammation markers C-reactive protein (CRP), interleukin-6 (IL-6) and other markers of inflammation were shown to be increased in lung disease." (PMID 26421427, 2015). "A comparison of lung diseases in GC showed significantly higher CRP levels in bronchopneumonia than in ILD (p = 0.0268), but not in other diseases." (PMID 38250933, 2024). "While raised levels of CRP are by no means specific to TB, this marker does appear to be the strongest differentiator between this and other lung diseases." (PMID 33717089, 2021).
lung disease (continued). "Without PS matching, the two groups showed significant differences in age, BMI, sex, ASA PS, smoking history, operator, surgical strategy, DM, HTN, IHD, pulmonary disease, clopidogrel, HMG-CoA reductase, NSAIDs, selective COX-2 inhibitor, CRP, AST, albumin, and echocardiographic/PFT findings." (PMID 31159309, 2019). "In those with pulmonary disease, smear positive cases had a higher CRP than smear negative cases: 67 mg/L (31–122 mg/L) vs 24 mg/L (7–72 mg/L), p < 0.001." (PMID 27287260, 2016). "Although C-reactive protein level is not affected by physical status, age, and sex, it may be used to early diagnose severe pulmonary disease secondary to bacterial infection." (PMID 35284429, 2021). "A set of three most significantly upregulated proteins (HBB, CRP and SERPINA1) and four most significantly downregulated proteins (APOA2, AHSG, KNG1 and AMBP) were selected for validation in an independent cohort of IPF and other lung diseases using ELISA test." (PMID 28122020, 2017). "There was a trend towards a significant positive correlation between the percentage of TLR4+ non-classical monocytes and c-reactive protein levels (Rho = 0.457, P = 0.075) and the VAS of pulmonary disease activity (0.52, P = 0.006)." (PMID 32164729, 2020).
peripheral arterial disease (92 papers, 2007 to 2026). A disorder of the arteries supplying the upper and lower extremity and the visceral organs. "CRP is a marker for systemic inflammation and is a risk predictor for symptomatic peripheral arterial diseases." (PMID 22958438, 2012). "The association of CRP with peripheral artery disease tended to be stronger compared to MI‐CAD." (PMID 34032303, 2021). "Higher levels of soluble intercellular adhesion molecule-1 (sICAM-1) and soluble vascular cell adhesion molecule-1 (sVCAM-1) have been associated with an increased risk of ischaemic disease and peripheral artery disease mediated, in part, by C reactive protein (CRP)." (PMID 24083393, 2013). "Moreover, elevated levels of IL-6 and C-reactive protein (CRP) in the peripheral blood of periodontal patients was found to predispose to an increased risk of developing peripheral arterial diseases which are regarded as an independent risk factors for developing cancer." (PMID 35047982, 2020). "Patients with peripheral arterial disease have elevated levels of hs-CRP, and it appears to be predictive of disease progression, as measured by the ankle–brachial index, and the severity of functional impairment." (PMID 38672153, 2024). "Potential confounding variables such as age, the existence of peripheral artery disease, and CRP levels were accounted for in the model." (PMID 39459635, 2024). "Another study conducted among 144 healthy men followed for 60 months reported that CRP is a predictive indicator for the development of peripheral artery disease." (PMID 36874319, 2023). "Physiologically, CRP’s pro-inflammatory properties are evidenced by the presence of anti-(m)CRP antibodies in several autoimmune conditions, such as lupus nephritis, peripheral artery disease (PAD), and skin-related disorders." (PMID 37781355, 2023). "Specifically, data have demonstrated an increased association between peripheral arterial disease (PAD) and chronic inflammatory conditions as well as elevated CRP levels." (PMID 33754114, 2021). "The factors associated with increased risk of mortality were identified as aged over 70, having a long duration of dialysis, need of oxygenation, high CRP in laboratory data at diagnosis, high BMI, and complication of peripheral arterial disease." (PMID 34697570, 2021). "In this Research Highlight, we discuss our new findings concerning the different structural forms of CRP, their presence in peripheral artery disease, and their mechanism of action." (PMID 27738646, 2016). "We then investigated the presence of both CRP isoforms on microparticles in the plasma of control donors versus that of patients with peripheral artery disease (PAD)." (PMID 27738646, 2016). "While CRP is well studied in acute coronary syndromes, its predictive role in symptomatic peripheral artery disease (PAD) is less clear." (PMID 26321028, 2015). "In studies designed to identify plasma predictors of peripheral arterial disease (PAD), the downstream induced protein of IL-6, CRP, is strongly and independently associated with symptomatic PAD." (PMID 19936194, 2008). "It is worth noting that in our study, CRP levels were higher in women compared to men, which aligns with previous research on peripheral artery diseases, suggesting that oxidative stress and pro-inflammatory biomarkers may be higher in women than in men." (PMID 38390443, 2024). "Four risk factors could be confirmed as independent predictors for SSI CRP ≥ 1 mg/dL (p = 0.013), peripheral arterial disease (p = 0.039), operating time (p = 0.007) and revision operation (p = 0.000)." (PMID 34670594, 2021). "The aim of this study was to investigate the potential role of HMGB-1, OPG and several inflammatory mediators such as C-reactive protein (HsCRP), tumor necrosis factor-alpha and interleukin-6 (IL-6) on the presence and severity of peripheral artery disease in patients with T2D." (PMID 28789654, 2017).
peripheral arterial disease (continued). "The fact that, in our study, CRP levels were statistically significantly higher in the peripheral artery disease group than in the control group suggests that high CRP levels can be an independent predictor in peripheral artery disease patients, in accordance with other studies in the literature." (PMID 36874319, 2023). "Furthermore, CRP blood levels have been associated with reduced performance in the TMT in several patient groups experiencing ongoing peripheral inflammatory activity, such as those with peripheral arterial disease and brain cancer and aging populations." (PMID 35566411, 2022). "This study assesses the effect of inflammatory biomarkers: fibrinogen and C-reactive protein (C-RP) on the progression of peripheral arterial disease (PAD) in type 2 diabetic (T2D) patients." (PMID 23375154, 2013). "The aim of this study was to assess the prognostic performance of the C-reactive protein-to-albumin ratio (CAR) in predicting mortality and amputation of peripheral artery disease (PAD) patients undergoing endovascular therapy (EVT)." (PMID 41323643, 2025). "This study provides critical insights into the clinical characteristics and outcomes of patients with advanced peripheral arterial disease (PAD), stratified by high-sensitivity C-reactive protein (hsCRP) levels." (PMID 39941486, 2025). "Among the nonlipid biomarkers, high-sensitivity CRP was the strongest predictor for the development of peripheral arterial disease." (PMID 35054095, 2022). "However, contrary to these findings, Ziegler etal. demonstrated that inpatients with peripheral arterial disease, there was no significant correlationbetween CRP and platelet aggregation measured by PFA-100®." (PMID 31432979, 2019). "We found that the CVH score was inversely related to both the biomarker levels (homocysteine, CRP, and microalbuminuria) and the presence of subclinical disease markers (increased CIMT, carotid plaques, LV hypertrophy, LV systolic dysfunction, and peripheral arterial disease)." (PMID 29047374, 2017).